IL18 (interleukin 18)
Diseases named in the same sentence as IL18 in open-access papers (continued):
Sharing a sentence is not in itself a finding about the gene and the disease.
Obesity (continued). "Finally, the role of IL-18 in maintaining homeostasis is underscored by findings from studies involving IL-18 deficient mice, which demonstrated a predisposition to obesity and other metabolic disorders." (PMID 39126010, 2024). "Many studies in PCOS patients emphasize the presence of chronic low-grade inflammation pointing to important inflammatory factors, including those such as IL-18, associated with insulin resistance, obesity, or metabolic syndrome, and even predicting long-term cardiovascular mortality." (PMID 38396443, 2024). "IL-18 also protects against obesity and its associated systemic metabolic disorders." (PMID 38383607, 2024). "Moreover, Il18 knockout mice are susceptible to the development of hyperphagia, obesity, and insulin resistance." (PMID 38315242, 2024). "IL-6 produced during exercise may alter leptin in the ARC, affecting post-exercise eating behavior IL-18 knockdown mice cause hyperphagia, obesity, and insulin resistance." (PMID 39691381, 2024). "In women with obesity, weight loss was found to reduce the levels of IL18." (PMID 38139000, 2023). "A basic study in mice deficient in IL-18 signaling confirmed that the action of IL-18 in skeletal muscle could contribute to its anti-obesity effect." (PMID 36313762, 2022). "IL-18 has also been associated with obesity, and it may contribute to the liver disease development associated with IR." (PMID 36289606, 2022). "Also other studies have showed clear associations between SAT IL-18 expression and insulin resistance and obesity." (PMID 36644557, 2022). "IL-18 is another pro-inflammatory cytokine, produced by both hematopoietic cells and non-hematopoietic cells, which has been found to be increased in obesity and associated with the metabolic syndrome independently of obesity and insulin resistance." (PMID 34884217, 2021). "Interestingly, IL‐18 deficiency leads to obesity, insulin resistance and metabolic syndrome in mice." (PMID 32558991, 2020). "Moreover, it has been reported that in mouse with caspase-1 knocked out, obesity develops similar to mice with IL-18 deficiency." (PMID 32463311, 2020). "However, knockout mice deficient in IL-18 or IL-18 receptor cause hyperphagia, obesity and insulin resistance, and it is worth reassessing the role of IL-18 in the pathogenesis of obesity and insulin resistance." (PMID 31548850, 2019). "IL-18 levels are also associated with insulin resistance, glucolipid metabolism, and obesity." (PMID 30429827, 2018). "Similarly, obesity was found to be associated with increased IL‐18 gene expression in the adipose tissue as well as elevated IL‐18 plasma levels." (PMID 28508444, 2017). "In addition, circulating levels of IL-18 appear to be associated with a number of microvascular and macrovascular comorbidities of obesity and T2DM." (PMID 26930607, 2016). "Collectively these results are also in agreement with a divergence in diet induced thermogenesis between Il18 and Il18r1-KO mice, which might justify their different susceptibility to dietary obesity." (PMID 26656097, 2015). "IL-18 levels are also increased in AD risk diseases, including type-2 diabetes and obesity." (PMID 25147500, 2014). "Overall, our work strongly suggests that increased IL-18 plays an important role in AD, particularly in overlapping the biological underpinnings of the diseases that increase AD risk, such as obesity, type-2 diabetes and depression as well as when wider AD risk gene alleles are present." (PMID 25147500, 2014). "This independent association of OPN and IL-18 with obesity may aggravate inflammation status in obese individuals and affect insulin resistance as well." (PMID 23675517, 2013). "The results suggest that the −607 C/A polymorphism of the IL-18 gene may have a role in the development of obesity." (PMID 22531046, 2012). "In addition, there was an apparent association between the −607 C/A polymorphism in IL-18 and obesity in women." (PMID 22531046, 2012).
Obesity (continued). "This study determined whether the promoter polymorphisms of IL-18 gene were associated with obesity and anthropometric parameters in obese women." (PMID 22531046, 2012). "Carriage of the A allele at position −607 in the promoter of the IL-18 gene may have a role in the development of obesity." (PMID 22531046, 2012). "We recently demonstrated that sustained elevation of IL-6 in obese mice receiving IL-12+ IL-18 contributes to the delayed resolution of AP in obesity and is associated with increased production of osteopontin and tissue inhibitor of metalloproteinase-1 (TIMP-1)." (PMID 22815875, 2012). "Interestingly, increased levels of IL-18 have been found in the blood of patients with ischemic heart disease, type-2 diabetes, and obesity, which are all known risk factors for AD." (PMID 22898493, 2012). "Paradoxically, genetically modified mice with IL-18 deficiency have been reported to develop hyperphagia, obesity and insulin resistance, which might be reversed by recombinant IL-18 administration." (PMID 20331890, 2010). "Finally, while IL-18 deficiency leads to obesity, the peripheral injection of IL-18 suppresses appetite." (PMID 20376352, 2010). "Furthermore, increased serum levels of IL-18 have been associated with insulin resistance and obesity in humans." (PMID 20490358, 2010). "In order to investigate the possible roles of IL-18 in the pathogenesis of PCOS and its relationship with insulin resistance (IR), obesity and hyperandrogenism, the polymorphisms at positions -607 and -137 in the promoter of the IL-18 gene in PCOS patients has been investigated." (PMID 20964873, 2010). "Notably, IL-18 is elevated in overweight teenagers, correlating with different anthropometrical measurement of obesity and associated with sE-selectin, a marker for endothelial damage." (PMID 20169140, 2010). "In addition, loss of the fat-derived cytokine interleukin 18 (IL-18) leads to hyperphagia and obesity." (PMID 17448988, 2007). "This might explain the minor role of IL-18 in triggering obesity-associated metabolic diseases." (PMID 30717382, 2019). "Therefore, it can be inferred that the mechanism by which the IL-18 gene polymorphism might influence obesity is related to different IL-18 synthesis, secretion, and activity." (PMID 22531046, 2012). "In this sense, we unveil that IL‐18 seems not essential for WAT remodeling induced by prolonged fasting, despite our clinical finding supporting the idea that in human obesity, IL‐18 expression is positively related to the lipolytic enzymes in adipose tissue." (PMID 41508774, 2026). "The same trend toward increased levels of chemerin, MCP1, and IL-18, was observed in the obesity abnormal." (PMID 39940942, 2025). "Overexpression of IL-18-binding protein or global deletion of IL-18 or the IL-18 receptor led to obesity, hyperglycaemia and insulin resistance in 5- to 7-month-old mice." (PMID 39496966, 2025). "Adipocytokines are immunomodulatory proteins secreted by adipocytes that act in feedback loops linking obesity and cardiometabolic disease, which typically include leptin, adiponectin, interleukin (IL)-6, IL-18, and tumor necrosis factor-alpha (TNF-a)." (PMID 40486661, 2025). "Secondly, IL-1β, IL-6, TNF-α, and IL-18 are overexpressed in obesity, contributing to the development of nephropathy by promoting inflammation." (PMID 40703753, 2025). "Its activation leads to the release of pro-inflammatory cytokines, such as interleukin-1β (IL-1β) and interleukin-18 (IL-18), which reinforce obesity-related inflammation and metabolic impairment." (PMID 41301434, 2025). "Chronic inflammation is linked to obesity, generating proinflammatory cytokines such as TNF-α, IL-6, IL-1β, and IL-18 that activate NF-kB." (PMID 40703753, 2025). "Interleukin-18 (IL-18), another pro-inflammatory cytokine belonging to the IL-1 family, can be considered essential in the inflammatory state of patients with obesity." (PMID 41141350, 2025).
Obesity (continued). "The activation of the inflammasome and its target cytokines, IL-1β and IL-18, are important mediators in innate immunity and contribute to the development of obesity-induced inflammation and insulin resistance." (PMID 41301516, 2025). "Murphy at al. demonstrated that mice lacking NLRP1 develop spontaneous obesity and MetS, and activation of NLPR1 prevents obesity possibly through regulating IL-18 production." (PMID 40433411, 2025). "Another study demonstrated elevated plasma IL-18 in individuals with obesity with glycemic disorders compared to a group of healthy eutrophic patients, identifying a positive relationship between increased BMI and serum IL-18 concentration." (PMID 40004007, 2025). "Future studies should be focus on illustrating how NLRP1 balance the production of pro-inflammatory IL-1 β and anti-obesity IL-18." (PMID 40433411, 2025). "Among those, IL-18 and chemerin are primary inflammatory mediators in adipose tissue, emerging as promising biomarkers of obesity and cardiometabolic abnormalities with contrasting roles." (PMID 39940942, 2025). "Elevated IL-18 levels were already observed in several low-grade inflammatory conditions, such as obesity or prediabetes, but their importance within PCOS is controversial." (PMID 38540173, 2024). "IL-18, another important inflammatory factor produced by Caspase-1, is increased in obese individuals, and IL-18−/− mice exhibit obesity and insulin resistance." (PMID 38672517, 2024). "IL-18 KO mice on high-fat diets have been shown to develop more severe obesity and insulin resistance, indicating the role of IL-18 in metabolic syndrome." (PMID 39769266, 2024). "We observed increased levels of circulating IL-18 in our obese group compared to the controls, confirming that the proinflammatory status was active in patients with obesity." (PMID 40729297, 2024). "What is the functional outcome of targeting IL-6 trans-signaling in the presence of other cytokines (IL-1β, TNF-α, and IL-18) in obesity?" (PMID 39125976, 2024). "This highlights the caspase‐1‐independent role of the Nlrp1b1 inflammasome in IL‐18 production and its potential protective role in obesity." (PMID 38629728, 2024). "Cytokines secreted by adipose tissue, such as IL-1β, IL-10, and IL-18, are elevated in both obesity and AD." (PMID 39273520, 2024). "IL-18 has increased expression in obesity and can induce the production of copious amounts of IL-6, serving as an amplifier of IL-6 effects." (PMID 39063055, 2024). "The proinflammatory status in the obesity group is highlighted by the elevated circulating proinflammatory molecules that were quantified by ELISA, with IL-18 and MCP-1 as the only statistically significant changes between groups (obese vs. control)." (PMID 40729297, 2024). "Platelet counts, MCP-1, and IL-18 highlight large positive differences between the groups, as these parameters were significantly increased in patients with obesity." (PMID 40729297, 2024). "Mice deactivated for NLRP1 inflammasome were shown to spontaneously develop obesity due to the decreased IL-18 production and lipolysis." (PMID 38483771, 2024). "The main findings of the present study highlight the well-known proinflammatory status related to obesity and validated in our studied group through high levels of IL-18, MCP-1, CRP, monocytes, lymphocytes, and neutrophils compared with the control group." (PMID 40729297, 2024). "SWELL1 and key markers of inflammation (NLRP3, NLRP6, IL1B, IL18 and IL8) were also upregulated in VAT in obesity and T2D being significantly associated (P < 0.01) with PIEZO1 levels." (PMID 39707172, 2024). "Interestingly, IL-18 levels could serve as markers of metabolic disorders associated with obesity." (PMID 39275140, 2024). "It was demonstrated that patients with obesity had increased levels of IL-18 compared to healthy controls." (PMID 39275140, 2024).
Obesity (continued). "We detected increased mRNA levels of NLPR3 (P = 0.002), NLRP6 (P < 0.001) and its effectors IL1B (P = 0.002), IL8 (P = 0.047) and IL18 (P = 0.006) in VAT of patients with obesity and with obesity and T2D." (PMID 39707172, 2024). "It has also been noticed that elevated levels of IL-18 occur in people diagnosed with obesity, insulin resistance, hypertension and lipid disorders, which are components of the metabolic syndrome." (PMID 37847180, 2023). "Consistent with a role in glucose homoeostasis, IL-18 deletion in the mouse leads to obesity and insulin resistance." (PMID 37137910, 2023). "While increased levels of IL-18 have been observed in several models of obesity and the metabolic syndrome, the data on IL-18 in NAFLD have been far more ambiguous." (PMID 37342340, 2023). "Obesity predisposes to a chronic inflammatory state which is accompanied by higher levels of pro-inflammatory cytokines such as RANTES, TNF-α, IL-6 and IL-18." (PMID 36771387, 2023). "Many of the common secreted upstream regulators we identified, such as TNF, IL-1β, IFN-γ, IL-18, CD40L, IL-6, EGF, TGFβ, and IL-21, were previously reported to be associated with obesity and metabolic dysfunction." (PMID 36880999, 2023). "Strikingly, IL-18 has marked anti-obesity effects as interleukin administration prevents weight gain, while IL-18 loss is associated with increased adiposity and insulin resistance in mice models." (PMID 37819510, 2023). "NLRP1 is also an innate immune sensor, which produces IL-18 under metabolic stress and inhibits obesity and metabolic syndrome." (PMID 37214347, 2023). "Obesity is regarded as a kind of chronic inflammation and can increase the levels of TNFα, IL-1β, IL-6, and IL-18 within adipose tissue and systemically, such as through inflammasome activation in macrophages." (PMID 37526777, 2023). "NLRP1 mainly affected the blood glucose by reducing IL-18 production, inducing obesity and glucose consumption in mice and leading to significant IR." (PMID 36993972, 2023). "IL-18 has been reported to be elevated in inflammatory diseases and conditions such as, T2D, obesity, Alzheimer's disease, and ischemic heart disease." (PMID 36186138, 2022). "In this review article, we will present the possible links between inflammasome-mediated cytokines, obesity-associated NASH, and HCC development, and we will also discuss approaches to using IL-1β and IL-18 as therapeutic targets in the context of HCC." (PMID 36289606, 2022). "At the same time, clinical observations implicate IL-18 in various metabolic diseases including obesity, type 1 and 2 diabetes and nonalcoholic fatty liver disease (NAFLD)/nonalcoholic steatohepatitis (NASH)." (PMID 36313762, 2022). "IL18 activities in obesity and diabetes have been reported but studies remain observational and controversial." (PMID 36482059, 2022). "Together, these observations suggest that IL18-IL18r signaling in WAT adipocytes protects mice from obesity, insulin resistance and adipose inflammation by maintaining the homeostatic glucose metabolism and insulin signaling." (PMID 36482059, 2022). "In this pathophysiological context, a huge research effort has been brought to the study of cytokines (including IL-18) produced by the adipose tissue and upregulated during obesity." (PMID 36313762, 2022). "Later work showed that IL-18-/- mice developed hypercholesterolemia and hypertriglyceridemia before the manifestation of obesity suggesting a primary effect of IL-18 on the liver." (PMID 36313762, 2022). "Accordingly, levels of pro-inflammatory cytokines, including IL-1β and IL-18, have been found to be increased in subjects with obesity or respiratory diseases." (PMID 35806353, 2022). "IL18r-deficient (Il18r−/−) mice showed “conflicting” responses to dietary obesity and adipose tissue thermogenesis compared with the Il18−/− mice." (PMID 36482059, 2022).
Obesity (continued). "IL-18-/- mice displayed primary hyperphagia leading to obesity and insulin resistance in the liver, adipose tissue, and muscle." (PMID 36313762, 2022). "Our aim was to analyze levels of proinflammatory biomarker interleukin-18 (IL-18) in healthy controls and patients with polycystic ovary syndrome (PCOS) focusing on its association with obesity, clinical, hormonal, and metabolic characteristics." (PMID 35263047, 2022). "According to our observations, obesity and hypertriglyceridemia in PsA are intertwined with disease activity via IL-18 action." (PMID 35160217, 2022). "Importantly, the results of our study rather support the hypothesis that the association between PCOS per se and elevation of IL-18 levels is dependent on confounding factors such as obesity and insulin resistance which influence the cytokine levels resulting in low-grade inflammation in PCOS." (PMID 35263047, 2022). "The existence of such a loop between the hypothalamic neuropeptide Y and BAT-derived IL18 in response to obesity and thermogenic activation is plausible and merits further investigation." (PMID 36482059, 2022). "IL-18 enhances the maturation of T- and NK-cells, and increases the production of diverse pro-inflammatory cytokines, exacerbating obesity-induced systemic inflammation." (PMID 36558167, 2022). "In the present review, we summarize and discuss both the physiological actions of IL-18 in metabolism and its potential roles in pathophysiological mechanisms leading to the most common human metabolic disorders, such as obesity, diabetes and NAFLD/NASH." (PMID 36313762, 2022). "In accordance, hepatic transcriptional changes were observed in the liver of IL-18-/- mice before obesity onset." (PMID 36313762, 2022). "In the present review, we summarize and discuss the physiological roles of IL-18 in metabolism and its potential involvement in pathophysiological mechanisms leading to the most common human metabolic disorders, such as obesity, diabetes, and NAFLD/NASH." (PMID 36313762, 2022). "To assess the role of BAT-derived IL18 in HFD-induced obesity and insulin resistance, we fed Il18fl/flUcp1Cre and Il18fl/fl mice a HFD for 12 weeks." (PMID 36482059, 2022). "Interleukin-18 plays a key role in atherosclerosis and plays a role in appetite control and the development of obesity." (PMID 36358920, 2022). "Il18−/− mice have been reported to show higher insulin resistance, diabetes mellitus, obesity, and dyslipidemia, and their serum AHSG levels were higher than those of Il18+/+ mice; hence, our results are consistent with previous studies." (PMID 34708129, 2021). "Circulating plasma levels of several immuno-modulatory peptides, including TNFα, IL-6, IL-8, IL-10, IL-18 and C-reactive protein, were found to be elevated in human obesity." (PMID 34571976, 2021). "Studies have reported that pro-inflammatory cytokines like interleukin 6 and interleukin 18 are elevated in obesity and that this occurs in parallel with changes to other inflammatory mediators as well as the development of insulin resistance." (PMID 34086911, 2021). "Our results showed higher plasma levels of IL-6, IL-1β, TNF-α, IL-8, IL-12, and IL-18 in subjects with obesity before bariatric surgery when compared with the postoperative state." (PMID 34108550, 2021). "Maturation of IL-18 by NLRP1 inflammasome prevents obesity and metabolic syndrome by increasing insulin sensitivity and peripheral FA uptake, but most commonly IL-1β masks the activity of IL-18 during systemic inflammation." (PMID 32143623, 2020). "Although IL-18 has been described as marker for kidney injury, it is possible that higher urinary IL-18 mRNA levels reflect filtered mRNA from a systemic inflammatory response in obesity." (PMID 33273645, 2020). "For example, cranberries and raspberries dampened postprandial elevations of serum IL-6 and IL-18, respectively, in adults with obesity and T2D after a HF breakfast." (PMID 32605005, 2020).